ICOS (inducible T cell costimulator)
Diseases named in the same sentence as ICOS in open-access papers (continued):
Sharing a sentence is not in itself a finding about the gene and the disease.
lung cancer (16 papers, 2016 to 2026). A malignant neoplasm involving the lung. "ICOS/ICOSL might be associated with prognosis of lung cancer, and ICOS and its ligand may be potential therapeutic targets in non‐small cell lung cancer." (PMID 37850501, 2023). "Another study on draining lymph nodes of lung cancer found that the expression of ICOS in lymph nodes decreased." (PMID 37850501, 2023). "This at least shows that ICOS and its ligand are widely expressed in lung cancer." (PMID 37850501, 2023). "However, higher infiltration of ICOS+ cells into lung cancer tumor tissues indicated longer OS period." (PMID 37850501, 2023). "ICOS has been shown to be expressed by PD-1+CD8+ T-cells after anti-PD1 therapy in lung cancer." (PMID 38127899, 2023). "A previous report on lung cancer also showed that the expression of ICOS is related to tumor size." (PMID 37850501, 2023). "Interestingly, however, we detected a decrease in ICOS expression in lung cancers such as NSCLC." (PMID 38616999, 2024). "Furthermore, a group from Stanford University reported successful developments in immune system visualization techniques using OX40 mAb for imaging OX40+ activated T cells in a mouse model of syngeneic lymphoma and 89Zr-DFO-ICOS mAb tracer, for detecting ICOS+ T cells in a murine lung cancer model." (PMID 37426447, 2023). "Polymorphisms in ICOS have been associated with pre-disposition to non-small cell lung cancer, while over-expression of YWHAZ is known to enhance proliferation and migration of lung cancer cells through induction of epithelial-mesenchymal transitions via beta-catenin signaling." (PMID 27145341, 2016). "Ours is the first comprehensive exploratory study of the expression and prognosis of ICOS and ICOSL in lung cancer in Chinese patients." (PMID 37850501, 2023). "ICOS was found to be positive in 58% (n = 31 of 54) of all lung cancer samples, and ICOS was categorized as negative in 42% (n = 23 of 54), low in 17% (n = 9 of 54), and high in 41% (n = 22 of 54)." (PMID 37850501, 2023). "This study explored ICOS and ICOSL expression and their correlation with clinical outcomes in human NSCLC using TCGA data mining; also immunohistochemistry analysis was performed using freshly resected tumor tissue from selected lung cancer patients." (PMID 37850501, 2023). "Given the previous analysis, we found that the expression of ICOS and ICOSL in tumor tissue was significantly correlated with survival, so we utilized a multivariate analysis to evaluate whether ICOS and ICOSL could predict the prognosis of lung cancer." (PMID 37850501, 2023). "All these results suggested that ICOS and ICOSL could be used as predictors of lung cancer prognosis." (PMID 37850501, 2023). "Firstly, patients with lung cancer treated with PD-1 inhibitors have a highly specific subset of proliferating CD8+ T cells in the peripheral blood, expressing effector-like phenotypes (HLA-DR+, CD38+, Bcl-2lo), costimulatory molecules (CD28, CD27, ICOS), and high levels of PD-1." (PMID 35484541, 2022). "However, the roles of ICOS/ICOSL in lung cancer are not very clear." (PMID 37850501, 2023).
Immunodeficiency (15 papers, 2011 to 2025). Failure of the immune system to protect the body adequately from infection, due to the absence or insufficiency of some component process or substance. "ICOS deficiency causes common-variable-immunodeficiency in humans which has been recently reclassified as a combined immunodeficiency." (PMID 31283790, 2019). "However, ICOS, an immunostimulatory factor, is crucial in humans, where its deficiency leads to common variable immunodeficiency, predisposing individuals to frequent bacterial infections in the respiratory and digestive tracts." (PMID 40395233, 2025). "In addition, we highlight the crucial role of ICOS+ Tregs in various immune diseases and outline its diagnostic and therapeutic effect in autoimmune responses." (PMID 32983168, 2020). "Recently, an increased susceptibility to viral and opportunistic infections has been described in ICOS-deficient patients thus suggesting that innate cells may be also affected in this combined immunodeficiency." (PMID 31283790, 2019). "This panel screens for major monogenic immunodeficiencies, including predominantly antibody deficiencies (e.g., TNFRSF13B/TACI, ICOS, CD19, IKBKB), combined immunodeficiencies, phagocytic and innate immunity defects, and complement pathway deficiencies." (PMID 40918823, 2025). "Here, we briefly introduce the role of ICOS+ Tregs in immune tolerance using several typical immune diseases as examples." (PMID 32983168, 2020). "IPA analyses showed that ICOS is mainly involved in iCOS-iCOSL signalling in T-helper (Th) cells, primary immunodeficiency signalling and the Th cell differentiation pathway." (PMID 28475033, 2017). "Our data suggest that individuals with ICOS deficiency may have progressively worsening defects in their EM CD4 T cell mediated protection, perhaps leading to progressively worse immunodeficiency and recurring infections." (PMID 21364749, 2011). "Furthermore, because ICOS plays an important role in the pathogenesis of many immune disorders, understanding the molecular mechanisms by which ICOS is regulated may create new opportunities for therapeutic interventions." (PMID 23923047, 2013). "ICOS is a CD28 and CTLA-4 cell-surface receptor family protein, which functions in immunodeficiency biological processes." (PMID 26457008, 2015).
common variable immunodeficiency (14 papers, 2014 to 2022). "Homozygous deletion of the ICOS gene in patients with common variable immunodeficiency (CVID) leads to suppression of Treg induction and loss of auto-tolerance." (PMID 35955790, 2022). "Although ICOS was the first described gene associated with a common variable immunodeficiency (CVID)–like phenotype, to date, only four different mutations have been identified in a total of 15 patients." (PMID 31858365, 2020). "Mutations in the ICOS gene is a cause of common variable immunodeficiency (CVID) in humans, which profoundly affects different aspects of T and B cell immune responses." (PMID 31283790, 2019). "In humans, homozygous ICOS deficiency results in common variable immunodeficiency (CVID), a condition characterized by aberrantly low serum gammaglobulin concentration." (PMID 27559335, 2016). "In humans, ICOS mutations are correlated with common variable immunodeficiency." (PMID 28290526, 2017). "Mutations in the ICOS gene encoding for costimulatory receptor for inducible T cell activation can present with common variable immunodeficiency (CVID) resulting in recurrent bacterial and viral infections, splenomegaly, and colitis." (PMID 34122435, 2021). "Other PID have leaky B cell development with alterations of the B cell diversity autoimmunity and B cell malignancies, jointly termed common variable immunodeficiency (CVID) and include PID with mutations in BAFF and the BAFF receptor TACI, BLNK/SLP65 (mouse) and ICOS (expressed on Tfh cells)." (PMID 33240268, 2020). "Mutations in ICOS (or its ligand, ICOSL) in humans are part of a class of mutations leading to the development of common variable immunodeficiency (CVID)." (PMID 31978191, 2020). "Common variable immunodeficiency (CVID) due to ICOS mutations was discovered by the identification of a small number of patients whose T cells lacked ICOS expression following in vitro stimulation." (PMID 31552044, 2019). "Patients lacking ICOS display a common variable immunodeficiency (CVID) with reduced circulating Tfh cells." (PMID 30666254, 2018).
Sjögren’s syndrome (14 papers, 2011 to 2025). "ICOS and PD-1 expression in cTfh is reported to be increased in several immune-related diseases, such as ulcerative colitis and multiple sclerosis, or associated with disease severity in such conditions as Primary Sjogren’s Syndrome." (PMID 35069575, 2021). "The cTfh to cTfr ratio indicated ectopic lymphoid structure formation in minor salivary gland, strongly associated with B cell, CD4+ T cell, and PD-1+ICOS+ T cell infiltration in minor salivary gland and allowed discrimination between Sjogren’s syndrome patients and healthy donors." (PMID 31382877, 2019). "Consequently, ICOS may be considered as an important pathogenic factor in primary Sjögren’s syndrome." (PMID 41301757, 2025). "Another important finding of this study was a higher membrane expression of ICOS (mICOS) on T cells from the PBMCs of patients with primary Sjögren syndrome." (PMID 35723338, 2022). "The ICOS+PD-1+ cTfh cells and IL-21 producing CD4+CXCR5+PD-1+ T cells were also shown to be significantly higher in patients with Sjögren syndrome." (PMID 33465845, 2021). "In the present study, given the importance of ICOS as a mediator of inflammation, we analyzed polymorphisms of ICOS (IVS1 + 173 T/C and c.1624 C/T) in primary Sjögren’s syndrome which have not been previously studied in this disease." (PMID 35723338, 2022).
asthma (13 papers, 2009 to 2026). "The inducible costimulatory ligand, ICOS-L, was also shown to play a role in an experimental asthma model as ICOS-deficient mice showed decreased Th2 response and ICOS–ICOS-L proved to be essential for the induction of T regulatory cells." (PMID 28439267, 2017). "ICOS deficiency was observed to restrain the suppressive ability of Tregs in controlling asthma, as the transfer of Icos–/– Tregs into OVA-sensitized recipients could not suppress the severe allergic phenotype." (PMID 32983168, 2020). "ICOS upregulation is relevant to disease activity in a variety of inflammatory diseases, such as inflammatory bowel disease and asthma." (PMID 37628716, 2023). "Overall, ICOS+ Tregs work with multiple types of immune cells to establish immune tolerance to asthma, which demonstrates their utility as a therapeutic or in the strategies for the prevention of allergic airway diseases." (PMID 32983168, 2020). "Numerous recent studies have revealed that Tregs and ICOS-ICOSL signals are highly involved in the anti-inflammatory process against asthma." (PMID 32983168, 2020). "The inhibition of ICOS and ICOSL have been discussed for some time also in regard to asthma associated host immune tolerance, however, yet a therapeutic application has to be developed." (PMID 30707726, 2019). "Inducible Costimulator (ICOS) is an important regulator of Th2 lymphocyte function and a potential immunotherapeutic target for allergy and asthma." (PMID 19888475, 2009). "ICOS deficiency was shown to impair the suppressive ability of Tregs in asthma and type 1 diabetes murine models, but no defects in GC reactions were reported." (PMID 36754569, 2023). "Interestingly, patients with asthma also display elevated levels of PD-1+ICOS+ Tfh2 cells and the ratio of Tfh2:Tfh1 cells positively correlates with the total IgE levels in the blood." (PMID 30158933, 2018). "Furthermore, disruption of ICOSL/ICOS pathway has been found to be beneficial when treating diseases dominated by Th2-type cytokine production,such as asthma." (PMID 25590646, 2015). "The present study demonstrates that BUD, an inhaled corticosteroid widely used for the management of bronchial asthma, controls asthma inflammation modulating ICOS, cell survival, Foxp3 and IL-10 expression differently in CD4+/CD25− and in CD4+/CD25+ cells in peripheral blood." (PMID 23251336, 2012). "Emerging evidences in animal models demonstrate a relevant role of ICOS in asthma." (PMID 23251336, 2012). "Work on the ICOS co-stimulation pathway in the airway already has provided promising results, with anti-ICOS treatment leading to prevention of chronic lung transplant rejection and obliterative bronchiolitis as well as ICOS being shown as an important player in asthma." (PMID 30319613, 2018). "IL7R, a component of the TSLP receptor, as well as ICOS and IL2RA, genes important in type 2 inflammatory responses, were increased in females with asthma compared to males with asthma." (PMID 41508394, 2026). "In correlation with the data on human samples, mRNA and protein expression levels of CXCR5, ICOS, ICOSL, and IL-21 were also elevated in mouse models of asthma." (PMID 30158933, 2018). "Researchers identified a critical role for ICOS:ICOSL signaling in the induction of ILC2-mediated cytokine production that led to airway hyperreactivity (AHR), an indicator of asthma." (PMID 27559335, 2016).
malaria (13 papers, 2009 to 2025). Malaria is a serious and sometimes fatal disease caused by a parasite that commonly infects a certain type of mosquito which feeds on humans. "Malaria uses ICOS+ T cells to promote the expression of the transcription factor T-bet and the secretion of the cytokine IFN-γ to promote its growth." (PMID 40316996, 2025). "Other functional and activation markers, Perforin, ICOS, and HLA-DR were increased on both Vδ2+ and Vδ1+ γδ T cells during malaria." (PMID 37968278, 2023). "Granzyme-B, ICOS and HLA-DR expression was higher on Vδ2+ compared to Vδ1+ γδ T cells during malaria." (PMID 37968278, 2023). "The lack of IL-6 only modestly affected Tfh cells by reducing the levels of ICOS expression in both malaria models." (PMID 36845571, 2021). "This study indicated that ICOS plays a part in modulating Th1 immunity which supports cerebral pathology in malaria." (PMID 30631323, 2018). "ICOS signaling regulate transcription factor T-bet, which is also involved in regulation of malaria parasite growth and pathogenesis." (PMID 29892278, 2018). "This study showed that ICOS expression has a deleterious effect on protective Th1 immunity against malaria but is necessary for maintenance of a sustained high-affinity, protective antibody responses." (PMID 30631323, 2018). "Additionally, higher proportions of Th1 cells also expressed CTLA-4, TIM-3, CD38 and ICOS during malaria." (PMID 37968278, 2023). "As such, we assessed the impacts of age and malaria on ICOS and Ki67 expression on Tfh cells." (PMID 35851033, 2022). "Altogether, this suggested the critical involvement of ICOS in malaria parasite growth and lethality might be through IFN-γ production." (PMID 29892278, 2018). "Thus, modulation of ICOS expression and its signaling might be helpful in altering parasite growth and lethality, which might be valuable in preventing severe malaria in humans." (PMID 29892278, 2018). "Consistent with scRNAseq data, at day 0 during malaria, there was significantly higher proportion of Tr1 cells expressing CD120b, CTLA-4, TIM-3, PD1, CD38 and ICOS." (PMID 37968278, 2023). "In particular, we identified higher percentages of activated malaria-specific CD4+ T cells expressing OX40, CD137, and ICOS in primigravid compared with multigravid women." (PMID 37634385, 2023). "Together, these data suggest that percentages of malaria-specific AIM+ CD4+ T cells, AIM+ Tfh cells, as well as OX40+ICOS+ cells, are higher in primigravid compared with multigravid women." (PMID 37634385, 2023). "In Malian children (age 6–12), P. falciparum malaria robustly activated cTfh cells, with increased expression of ICOS, HLA-DR, CD38 and Ki67 detected within cTfh cells during malaria compared to post-treatment." (PMID 36845571, 2021). "Taken together, our results depicted the importance of ICOS expressing CD4+ and CD8+ T cells in malaria parasite growth and lethality through IFN-γ production and T-bet expression." (PMID 29892278, 2018). "However, we found that the frequency of ICOS expressing cells was significantly increased in the memory, activated memory and total CD4+ T lymphocyte compartments in malaria patients BT." (PMID 28700710, 2017). "Using a co-culture system of malaria-infected red blood cells (iRBCs) and peripheral blood mononuclear cells from healthy individuals, we found that two populations of Foxp3hi and Foxp3int CD4+CD25hi T cells with a typical Treg phenotype (CTLA-4+, CD127low, CD39+, ICOS+, TNFRII+) were induced." (PMID 19680449, 2009). "Furthermore, ICOS is linked to Tr1 development and activity, and recent studies show that systemic IL-27 and ICOS cooperate to regulate Tr1 activity during experimental malaria; however, in these reports neither IL-27R signaling nor ICOS was essential for Tr1 development during P. yoelii malaria." (PMID 27732671, 2016).
malaria (continued). "Similarly, Icos−/− mice show intact TFH differentiation for as long as 6 days following infection with the non-lethal strain of malaria, Plasmodium chabaudi, indicating that early TFH differentiation can occur in an ICOS-independent manner in some models." (PMID 30405612, 2018).
type 1 diabetes (13 papers, 2012 to 2024). "The impact on Tfh cells was also studied in a model of type 1 diabetes, showing that Tfh and other ICOS+ CD4+ T cell subsets are the most sensitive to the effect of abatacept." (PMID 38567291, 2024). "ICOS has a key role in controlling effector functions and survival of Tregs in models of oral and respiratory tolerance, as well as type 1 diabetes." (PMID 34752418, 2021). "Data showing reduced ICOS+ Treg frequencies in the pancreatic tissue in a mouse model of type I diabetes further support this notion." (PMID 30319662, 2018). "Out of the 69 regions reported in the GWAS catalog for type 1 diabetes, eight overlap with the regions reported in this study and out of those eight, CTLA4/ICOS also overlap with the previously reported CD associations." (PMID 23936387, 2013).